Y_RNA (Y RNA )
Gene: Miscellaneous RNA gene on chromosome 19 (46,736,312 to 46,736,419, forward strand). Ensembl gene ENSG00000222614.
Homologues: Orthologues: chimpanzee Y_RNA (98% identical). Paralogues in human: Y_RNA (73% identical), RNY1 (71% identical), Y_RNA (71% identical), RNY1P8 (70% identical), Y_RNA (70% identical), Y_RNA (69% identical), RNY1P11 (68% identical), RNY1P2 (68% identical), Y_RNA (68% identical), RNY1P15 (67% identical), RNY1P5 (67% identical), RNY1P7 (67% identical), and 85 more.